CD1D (CD1d molecule)
Diseases named in the same sentence as CD1D in open-access papers (continued):
Sharing a sentence is not in itself a finding about the gene and the disease.
infection (continued). "Because of the central role of NKT cells in producing IL-4 early after infection, we wondered whether CD1d−/− mice would have reduced numbers of IL-4-secreting cells." (PMID 29249358, 2018). "In the same line, oral infection of mice with Yersinia enterocolitica (which adhere to epithelial and M cells and translocate through IECs) resulted in an increased number of bacteria found in the mLN of CD1d−/− mice in comparison with littermate controls." (PMID 29378774, 2018). "By oral infection of mildly virulent strain ME49 T. gondii cysts, most CD1d-deficient C57BL/6 mice died within 2 wk of infection compared to no death in WT mice." (PMID 27563682, 2016). "By the use of CD1d KO mice, it was found that iNKT cells contributed to resistance against this protozoan and to the control of inflammation in the colitis induced by the infection." (PMID 27563682, 2016). "However, infection with some viruses (e.g., dengue virus) leads to upregulated CD1d expression consistent with iNKT cell activation while certain others (e.g., herpesviruses and HIV) downregulate CD1d to plausibly evade detection by iNKT cells." (PMID 26697007, 2015). "Similarly, adoptive transfer experiment also suggested that activation of iNKT cells in vivo in EV71M infection also requires CD1d molecule." (PMID 25615690, 2015). "Together, these findings suggest that herpesvirus may activate early iNKT cell responses during infection by inducing the presentation of endogenous lipids antigens on CD1d." (PMID 26161082, 2015). "At the higher dose of EV71M infection (2×105 PFU), all 16 CD1d-deficient mice developed limb paresis after 7 days post-infection, and none survived beyond 14 days." (PMID 25615690, 2015). "Hence, CD1d-deficient animals have a tempered inflammatory response and perform clinically better in response to intranasal LVS infection." (PMID 26068662, 2015). "During infection, recognition of inducible self-lipid antigens in combination with stimulation by the inflammatory milieu through cytokines, or direct recognition of microbial antigens results in the rapid activation of CD1d-restricted T cells." (PMID 26284062, 2015). "Because F. tularensis is able to infect and replicate within neutrophils, these cells likely serve as a vehicle for dissemination from the primary site of infection, which might contribute to the reduced peripheral burden observed in CD1d-/- mice." (PMID 26068662, 2015). "The observation that the in vivo IFNγ response was almost entirely CD1d-dependent suggests that our in vitro infection model may be over-estimating the effect of cytokine-driven stimulation." (PMID 24391492, 2014). "Furthermore, in mice, which only express CD1d molecules, iNKT cells were shown to be important for control of early infection." (PMID 24286535, 2013). "This means that CD1d dependent innate immunity may be directed to both exogenous and endogenous antigens during infections." (PMID 21255407, 2011). "In addition, infection of immature human DC with L. infantum results in increased CD1d cell surface expression, and subsequent increased recognition and killing by IFNγ-producing iNKT cells." (PMID 18463695, 2008). "Thus, NKT cells and CD1d function as a major innate pathway for the detection of these microbial cell wall components and promote rapid microbial clearance upon infection in vivo." (PMID 18474357, 2008). "This might also be consistent with the acquisition of NK1.1 as a marker on conventional T cells in CD1d-KO mice, although there were only 3 clones that were uniquely identified in CD1d-KO mice upon infection, suggesting the potential of this to occur would be very limited." (PMID 39088280, 2024). "Particularly in dLNs, enhanced production of Ccl8 and Ccl7 was observed in CD1d-KO mice compared with WT mice, which, being monocyte and DC chemoattractants, could enhance the trafficking of those cells infected already as well as potential infection targets." (PMID 39088280, 2024).
infection (continued). "cDC1 cells from both uninfected wildtype and uninfected Bcl3flx/flxZbtb46 cre mice expressed similar levels of genes related to antigen presentation except those related to MHC class Ib genes (H2-M3, Mr1, Cd1d), which seemed to be affected by Bcl3 deficiency even in the absence of infection." (PMID 36318581, 2022). "We hypothesize that this altered lipid composition of the MIL-R membrane directly results in increased NK and NKT cell activation and enhanced presentation of lipid antigens by CD1d molecules on dendritic cells and Kupffer cells following infection with the experimental MIL-R strain." (PMID 34292975, 2021). "Furthermore, we detected a reduction in the surface expression of CD1d in CD11b+ DCs, epithelial cells, and alveolar macrophages in hRSV-infected mice, while this reduction of CD1d was only seen in alveolar macrophages during an infection of mice with hMPV." (PMID 32463330, 2020). "On the other hand, the lack of differences during an hMPV infection found between the wild-type and the CD1d-deficient mice could be associated with hMPV not inducing the activation or proliferation of the CD1d-restricted NKT cells." (PMID 32463330, 2020). "Subsequently, to check whether the recovery of the initial IL-4 wave could rescue the germinal center defect observed in NKT cell-deficient mice, we administered PBS or IL-4 complexed with an anti-IL4 antibody (IL-4c) to groups of CD1d−/− mice during the initial 2 days of infection." (PMID 29249358, 2018). "There currently exists an unmet need to track and quantify CD1d-mediated presentation of pathogen-derived lipids and to investigate the characteristics of the immunological synapses formed between CD1d+ Ag-presenting cells (APCs) and iNKT cells during infection." (PMID 26697007, 2015). "Our studies suggested that HSV-1 UL56 gene is a major viral protein involved in downregulating CD1d expression and suppressing NKT cell function during infection." (PMID 40047437, 2025). "During productive infection of human B cells with EBV, a gammaherpesvirus closely related to KSHV, the degradation of CD1d at a transcriptional level by the EBV shutoff protein BFL5 had been reported." (PMID 39355244, 2024). "Overall, our study identified that the capsid protein p72 on the ASFV virions binds to the host membrane factor CD1d, which further recruits EPS15 to form the p72-CD1d-EPS15 complex, finally leading to endocytosis of ASFV virions during ASFV infection." (PMID 37254454, 2023). "Both NKT cell types recognize antigens in the context of CD1d, and it was observed that T. cruzi infected CD1d-/- mice, which lack type I and II NKT cells, have a milder infection with reduced liver mononuclear cell infiltration." (PMID 35720410, 2022). "Although we observed a robust production of IL-4 in CD169-DTR/wild-type chimeras by day 3 of infection, NKT cells from CD169-DTR/CD1d−/− chimeras were impaired regarding this cytokine." (PMID 29249358, 2018). "To gain insight into the spatial distribution of these IL-4-producing NKT cells, we infected wild-type, CD1d−/−, and IL-4 GFP reporter mice with influenza virus and harvested mediastinal lymph nodes after infection." (PMID 29249358, 2018). "Eight genes (NCF4, CD14, IL17D, CD1D, CD163, IL1R2, TLR9, and TLR2) with different expression in each infection group were selected for qPCR analysis." (PMID 25906258, 2015). "Infection with either VV or VSV resulted in reduced activation of iNKT cells, although CD1d surface levels remained unchanged." (PMID 23202469, 2012). "On day 1.5 post-infection, the percentage of hepatic IFN-γ+ Vα14i NK T cells in mice that received the anti-CD1d mAb or control IgG was comparable." (PMID 18636102, 2008). "In contrast, once infection is established, iNKT cells are recruited to the lung and Mφ upregulate cell surface CD1d; however, this is coincident with the appearance of conventional T cells in the lung, which may overshadow the contribution of CD1d-restricted T cells." (PMID 19079582, 2008).
infection (continued). "Although only a limited physiological role was found for CD1d-restricted NKT cells during experimental VL, the activation of these cells has been shown to improve disease outcome in many infections, often via the increased production of IFNγ." (PMID 18463695, 2008). "We observed significantly higher numbers of both newly recruited CFSE–CD8+ T cells and tissue-resident CFSE+CD8+ T cells in the FPs of WT mice compared with CD1d-KO mice on day 3 after infection, yet no changes at baseline." (PMID 39088280, 2024). "A marked depletion of type I NKT cells was observed in the peripheral blood samples of SARS-CoV-2 infected patients, a finding which was found to be independent of CD1d downregulation during infection." (PMID 39355244, 2024). "Since the infection of human DCs is not efficient and most likely non-productive, we then used stable CD1d-expressing cell line for our study of CD1d downregulation and identification of viral gene(s) responsible for the evasion of CD1d function." (PMID 36961850, 2023). "Unlike in control mice there was no significant increase in IL-4 or IL-13 serum levels in CD1d-/- mice detectable at day 5 pi suggesting that iNKT cells are major producers of these cytokines during early infection." (PMID 36159876, 2022). "The results from the current study showed a rapid expansion of B220+CD5+CD1d+ IL-10 producing regulatory B cells during infection with both lethal strain P. yoelii 17XL and non-lethal P. yoelii 17XNL at an early stage of infection." (PMID 35625397, 2022). "Given the early IFN-γ response at day 1 of infection, NK (TcRβ- NK1.1+), NKT (TcRβ+ CD1d tetramer+), CD4+ T (TcRβ+ CD4+) and CD8+ T (TcRβ+ CD8+) cell populations were examined in the liver and spleen of MIL-SPpyRE9/DsRed and MIL-RPpyRE9/DsRed infected C57Bl/6 mice." (PMID 34292975, 2021). "We confirmed that the majority of CD4+NK1.1+ T cells were truly type II NKT cells, since this population was reduced in CD1d-/- mice and did not expand in CD1d-/- mice relative to B6 and Jα18-/- mice after SA infection." (PMID 33312179, 2020). "However, it has been reported that infection-induced activation of MZB cells, as well as their pathogen-specific IgM production depend on the expression of CD1d." (PMID 32635160, 2020). "Also, 4 weeks after infection, significantly higher percentage of activated, CD86 positive, CD11c+, CD11c+CD11b+, and CD11c+CD1d+ dendritic cells was detected in the livers of WT compared with Lgals3−/− mice." (PMID 31231399, 2019). "Although CD1d-tetramer+ cells were nearly undetectable in uninfected animals, they were observed inside B cell follicles and in direct contact with CD169+ macrophages at the subcapsular sinus and interfollicular areas by day 3 of infection." (PMID 29249358, 2018). "To assess the contribution of NKT and TfH cells to the pool of IL-4-producing cells at different times of infection, we gated on TCRβ+ IL-4-GFP+ lymph node cells and analyzed the proportion of this population that was CD1d-tetamer+ (NKT cells) or CXCR5+ (TfH cells)." (PMID 29249358, 2018). "However, this pulmonary eosinophilia was abrogated in CD1d KO mice, suggesting that eosinophil infiltration following RSV re-infection is CD1d-dependent." (PMID 28570692, 2017). "In the absence of gp150, however, HLA I, II, and CD1d surface levels were significantly higher during productive infection, as visible when comparing gp350+ AkataΔgp150 to Akata wt cells (compare tinted with non-filled grey histograms)." (PMID 27077376, 2016). "Hepatic NKT cells consisted mainly of CD1d-dependent CD4+ and double negative NKT cells, whereas splenic NKT cells presented a CD1d-independent TCRhigh CD4high phenotype during infection." (PMID 27446022, 2016). "By d14, fewer than 50% B6 and almost all CD1d-/- mice regained weight and showed no outward signs of disease, surviving the infection." (PMID 26068662, 2015).
infection (continued). "This is in contrast to the findings showing that iNKT cell activation triggered by the infection of MCMV is not dependent on CD1d molecule." (PMID 25615690, 2015). "Furthermore, we adoptively transferred purified iNKT cells into 7-day-old WT mice and CD1d-/- mice and determined the CD69 expression levels of iNKT cells upon EV71M infection." (PMID 25615690, 2015). "Infection by various microbes including Salmonella, Aspergillus, and E. coli LPS, induce iNKT cell activation by a combination of IL-12, IL-18, and/or TCR stimulation through interaction with CD1d." (PMID 24391492, 2014). "Thus, although CD1d-independent GM-CSF and IFNγ was observed in vitro, TCR signaling is crucial in vivo during infection to stimulate iNKT cells to produce cytokines." (PMID 24391492, 2014). "We report that mouse infection with N. aromaticivorans induced antimitochondrial IgG antibodies and the development of chronic bile duct lesions and lymphoepithelioid granulomas similar to PBC, in a CD1d-dependent manner." (PMID 18474357, 2008). "While another study found that anti-CD1d mAb treatment did not worsen the pulmonary Mtb burden following low dose aerosol infection, early time points were not examined." (PMID 19079582, 2008). "Although less severe than in the NOD 1101 background, liver lesions clearly developed in B6.scid recipients of spleen cells collected at week 12 post-infection in CD1d+/− mice but not CD1d−/− mice, confirming the key role of NKT cells in disease." (PMID 18474357, 2008). "First, we infected WT and CD1d-KO mice with DENV2 (2 × 105 PFU) via s.c. injection and determined the relative NKT cell subtypes present in the FP skin and dLN by flow cytometry at days 3 and 5 after infection, which were defined based on cellular markers identified in prior reports." (PMID 39088280, 2024). "The higher viral load in the dLNs of CD1d-KO mice despite the unaltered CTL response at that site suggested other mechanisms leading to the amplification of DENV infection in the dLNs might exist, aside from merely impaired CTL-mediated clearance of infection." (PMID 39088280, 2024). "Furthermore, significantly increased numbers of NKT-like cells were present on days 3 and 5 after infection in the FPs but not dLNs of WT mice, but not in CD1d-KO mice." (PMID 39088280, 2024). "Importantly, the knockdown of CD1d expression, blocking the host cells with anti-CD1d antibody, and pre-incubation of the virions with recombinant CD1d proteins all dramatically blocked ASFV infection, highlighting its critical role in viral entry." (PMID 37254454, 2023). "Infection with murine cytomegalovirus induces CD1d‐independent IFN‐γ (but not IL‐4) secretion by iNKT cells in the absence of expansion 46, suggesting that in vivo activation of iNKT cells in the absence of TCR signaling may not lead to proliferation." (PMID 30427069, 2019). "Flow cytometry analysis revealed that, although conventional CD4+ T cells gradually express CXCR5, PD-1, Bcl6, and SLAM and produce high levels of IL-21 after infection, TCRβ+CD1d-tetramer+ NKT cells do not upregulate Bcl6, CXCR5, or PD-1 and express moderate levels of SLAM and IL-21." (PMID 29249358, 2018). "In contrast to DCs, CD1d is not downregulated on keratinocytes after infection with HSV-1." (PMID 29616036, 2018). "In our study, the animals that received the anti-CD1d antibody were not protected from infection." (PMID 26114123, 2015). "However, infection with the small single-stranded RNA virus lymphocytic choriomeningitis virus (LCMV) had no direct effect on NKT cell activation and thus interference with CD1d-restricted antigen presentation seems to be virus-specific." (PMID 23202469, 2012). "It will be very interesting to further investigate whether during in vivo infection, the suppression of NKT cell function by UL56 collaboarates with that of US3, given that we demonstrated that these two viral proteins collaborate with each other to efficiently downregulate CD1d expression." (PMID 40047437, 2025).
infection (continued). "Intranasal exposure to the iNKT cell ligand α-galactosylceramide (α-GC) with RSV primary infection in neonatal mice elicited neither cytokine production (except for a slight increase of IL-5) nor pulmonary eosinophilia, despite the presence of both CD1d+ cells and NKT cells." (PMID 28570692, 2017). "Moreover, in murine B. burgdorferi infection, CD1 d presentation of a borrelial glycolipid to NK T cells was important in the early innate immune response, possibly as a source of IFN-γ, and CD1d-/- mice did not control the infection as well as their wild-type counterparts." (PMID 20828409, 2010). "At 16 hours post infection, while CD1d was clearly downregulated in cells infected by wild-type HSV-1 viruses, there is no detectable CD1d downregulation in cells infected with mutant viruses." (PMID 40047437, 2025). "CD1d-restricted NKT cells, which are also lacking in β2m-/- mice, constitute 20–30% of murine hepatic lymphocytes and, in some infections, play an important role in the early antimicrobial immune response." (PMID 27606708, 2016). "It is tempting to hypothesize that the absence of CD1d downregulation and NKT cell evasion during infection by E:N15A mutant virus is at least partially responsible for its reduced virulence in vivo." (PMID 36961850, 2023). "Because of the nonpolymorphic nature of CD1d molecules, targeting of type II NKT cells with a lipid antigen vaccine could be a novel method to induce protection against SA infections where previous vaccines have failed." (PMID 33312179, 2020). "It was also demonstrated that CD49b+ CD3+ natural killer T (NKT) cells increased in the liver after a primary infection with P. yoelii non-lethal strain (17XNL), and that CD1d-restricted NKT cells, which secrete IFNγ, are critical to reduce liver-stage burden in a secondary infection." (PMID 27446022, 2016). "In support of that hypothesis, we have previously shown that cross-linking of NK1.1 preferentially induces IFN-γ and no IL-4 production by CD1d-restricted NKT cells, suggesting a TCR-independent pathway of pro-inflammatory responses to infection." (PMID 24691125, 2014). "Although there is no direct evidence for CD1d antigen presentation being compromised during experimental VL, we sought to eliminate this possibility by delivering α-GalCer–loaded BMDC to mice 2 h prior to infection." (PMID 18463695, 2008). "We have observed induction of expression of the activation markers CD1d, CD25, CD31, and CD35 on mouse granuloma macrophages at different time points of latent tuberculous infection, and not on bone marrow macrophages after infection with the BCG vaccine in vitro." (PMID 27066505, 2016).